REN (renin)
Diseases named in the same sentence as REN in open-access papers (continued):
Sharing a sentence is not in itself a finding about the gene and the disease.
renal fibrosis (76 papers, 2011 to 2025). A final common manifestation of a wide variety of chronic kidney diseases characterized by glomerulosclerosis and tubulointerstitial fibrosis. "Some studies indicated that CTGF, Wnt/β-catenin, renin-angiotensin system, oxidative stress, and so forth, were implicated in renal fibrosis." (PMID 35227255, 2022). "Recent data suggest that renin is also implicated in the progression of renal fibrosis and direct rennin inhibition with Aliskiren attenuating inflammation and fibrosis induced by UUO." (PMID 26078807, 2015). "In addition, Klotho can inhibit the renin-angiotensin-aldosterone system, and the nuclear factor kappa B (NF-κB) signaling pathway inhibits renal fibrosis caused by the inflammatory response." (PMID 35692408, 2022). "Given renin content and At1aR and Tgfb1 mRNA expression were enhanced in male hypoxia-exposed offspring, this may be an underlying molecular mechanism for the widespread renal fibrosis in this group." (PMID 28811528, 2017). "Ang II, the biologically active peptides of the renin–angiotensin system, plays an importance role in regulating renal fibrosis and inflammation." (PMID 40141345, 2025). "Increasing evidence suggested that renin-angiotensin system (RAS) plays a central role in renal fibrosis." (PMID 40607249, 2025). "By activating the renin-angiotensin system, IS caused an EMT-like process both in vitro and in vivo, which further exacerbated renal fibrosis." (PMID 40520523, 2025). "Beyond these indirect pathways, visceral adiposity itself promotes a proinflammatory state (marked by TNF-alpha, IL-6, MCP-1) that drives renal fibrosis and activates the renin-angiotensin-aldosterone system, leading to glomerular hyperfiltration." (PMID 40834423, 2025). "In renal fibrosis, exercise regulates key molecules in lipid metabolism (such as PPARα) and the renin-angiotensin system, reducing lipid accumulation and slowing the progression of fibrosis." (PMID 40182630, 2025). "Intriguingly, the Wnt pathway is activated during aging in renin-producing cells of the afferent arterioles, leading to increased renin expression and age-related renal fibrosis." (PMID 39273497, 2024). "In another experimental study using hypertensive rats, goreisan administration reduced blood pressure by suppressing the renin–angiotensin–aldosterone system and prevented the progression of renal fibrosis." (PMID 39768446, 2024). "The renin–angiotensin–aldosterone system (RAAS) triggers a cascade leading to renal fibrosis, with aldosterone exacerbating the oxidative stress and cellular changes that promote fibrosis." (PMID 38339031, 2024). "In diabetic rats, the levels of the fibrosis-related factors TGF-1, PDGF, and TIMP-1 can be decreased by renin-angiotensin-aldosterone system inhibitors, which can also be used to treat renal fibrosis." (PMID 37266443, 2023). "Inactivated ClC will reduce the reabsorption of chloride and sodium in renal tubules, and the loss of NaCl and water will activate the renin-angiotensin-aldosterone system (RAAS), which will lead to the loss of potassium and renal fibrosis." (PMID 37063660, 2023). "PI polyamide administration also suppressed the increased expression of TGF-β1, α-SMA and renin mRNAs and histologically improved renal fibrosis in UUO kidney." (PMID 36018840, 2022). "Further, upregulation of renal NADPH oxidase via the renin–angiotensin system results in the ROS generation, which contributes to renal fibrosis." (PMID 36144240, 2022). "We previously reported that exercise training inhibited the Nx-activated renal renin–angiotensin system and renal fibrosis." (PMID 36144240, 2022). "The beneficial effect on renal fibrosis of inhibiting the renin-angiotensin system likely reflects the central role that angiotensin has in regulating renal function and structure by its various actions." (PMID 32728402, 2020).
renal fibrosis (continued). "Intrarenal renin–angiotensin system activation is one of the mechanisms induced in renal fibrosis in FA-induced ER stress in the kidney." (PMID 32575412, 2020). "In diabetic kidney disease (DKD) increased activation of renin‐angiotensin‐aldosterone system (RAAS) contributes to renal fibrosis." (PMID 30324679, 2019). "Nitric oxide is also closely involved in renal fibrosis and in the regulation of renal function, including glomerular filtration, tubular reabsorption, and renin secretion." (PMID 26824356, 2016). "To date, the inhibitors of renin-angiotensin-aldosterone system (RAAS) are the primary medications for renal fibrosis and myocardial remodeling, but the application of these drugs is limited when serum creatinine rises above 3.5 mg/dL." (PMID 26078807, 2015). "The treatment protocol is based on the reduction of proteinuria, intraglomerular pressure, and renal fibrosis via interference with the renin–angiotensin–aldosterone system." (PMID 22461141, 2013). "The renin-angiotensin system is a central player in multiple mechanisms responsible for the progression of renal fibrosis." (PMID 22403621, 2012). "It is well known that activation of the renin-angiotensin-aldosterone system is critical for development of cardiovascular and renal fibrosis in hypertension and diabetes." (PMID 19706694, 2011). "The pathophysiological changes involved in the progression of renal fibrosis include tubular epithelial cell apoptosis by either mechanical or oxidative stress, the activation of the renin–angiotensin–aldosterone system, NF-κB-mediated inflammation, and fibroblast activation." (PMID 38786096, 2024). "PRR may not only enhance prorenin-dependent activation of the renin–angiotensin system and MAPKs, but may also induce renal fibrosis through amplified activation of Wnt/β-catenin signaling by a prorenin-independent PRR mechanism." (PMID 39195649, 2024). "However, there is also an alternative Ang II-independent pathway that contributes to renal fibrosis by involving the renin–angiotensin system." (PMID 39195649, 2024). "A further study indicated that high-glucose stimulation could increase the renin expression and renin might have Ang II-independent actions to develop renal fibrosis." (PMID 32411800, 2020). "According to recent studies, renin-producing cells are rather plastic and may transform into other renal cell types, such as myofibroblasts, and thus they significantly contribute to renal fibrosis." (PMID 28753620, 2017). "However, proteinuria and renal fibrosis were identical in floxed and CD renin KO mice in the current study." (PMID 27467376, 2016). "The renin–angiotensin system (RAS) is a major regulator of renal fibrosis." (PMID 25954204, 2015). "This analysis formally tested a well-established hypothesis, that the renin-angiotensin-aldosterone system (RAAS) plays a role in renal fibrosis." (PMID 23060897, 2012). "Therefore, the binding of prorenin and PRR, blocked by PRO20, is expected to suppress the progression of renal fibrosis and abnormal renal function through inhibiting activation of the renin–angiotensin system to produce Ang II and prorenin/PRR-dependent intracellular signaling pathways." (PMID 39195649, 2024). "Furthermore, relaxins affect renal fibrosis and its correlation with members of the renin-angiotensin-aldosterone system may also influence reverse remodeling." (PMID 31231242, 2019). "For instance, the fact that the Black-Swiss strain carries two renin genes while the C57/BL6 only carries one has been suggested as a key difference, which distinguishes renal and cardiovascular phenotypes between these strains including susceptibility to renal fibrosis." (PMID 30158457, 2018). "Finally, (pro)renin/PRR may induce renal fibrosis through multiple intracellular signaling pathways, either alone or in concert with activation of renal tissue RAS." (PMID 28753620, 2017).
renal fibrosis (continued). "If targeting the renin–angiotensin system is now a well-admitted therapy for CKD, our data strongly suggested that a combination therapy associating an AT1a and a B1Ra might be much more effective to slow down the progression of renal fibrosis." (PMID 25698969, 2015). "Although all major components of the renin-angiotensin-aldosterone system can exhibit profibrotic activity, angiotensin II, the principal constituent peptide of the renin-angiotensin-aldosterone system, plays an important role in the development of renal fibrosis." (PMID 19706694, 2011). "Treatment options that inhibit the renin-angiotensin-aldosterone system (RAAS) effectively reduce proteinuria and slow CKD progression and renal fibrosis." (PMID 38610646, 2024). "Furthermore, increased PRR expression, associated with increased prorenin expression, may induce renal fibrosis through amplified activation of Wnt/β-catenin signaling by prorenin-independent PRR, in addition to enhanced activation of the renin–angiotensin system and MAPKs." (PMID 39195649, 2024). "Activation of the paraventricular nucleus (PVN) renin-angiotensin system (RAS) and sympathetic nervous system (SNS) are common mechanism of renal fibrosis." (PMID 39346076, 2024). "FTZ also substantially alleviated renal fibrosis and the mRNA expression of inflammation cytokines, NADPH oxidases, and the renin–angiotensin system in the renal cortex." (PMID 35846749, 2022). "p-Cresol sulfate that causes nephrotoxicity and vascular toxicity by activating the renal renin-angiotensin-aldosterone system (RAAS), and leads to renal tubular cell stress response cells and renal fibrosis is a uremic toxin." (PMID 33967748, 2021). "Experimental evidence has shown that (pro)renin and PRR participate in the development of renal fibrosis." (PMID 28753620, 2017). "A deregulated renin-angiotensin-aldosterone system (RAAS) was described to contribute to TL shortening and renal fibrosis as a result of oxidative stress and inflammation." (PMID 26149682, 2015). "Traditional therapy, centered on renin-angiotensin system blockers, can delay disease progression but fails to reverse renal fibrosis." (PMID 41487503, 2025). "Drugs in clinical use that are nephroprotective and can reduce renal fibrosis in both humans and experimental animal models of CKD include the renin-angiotensin blockers, mineralocorticoid receptor (MR) antagonists, and sodium/glucose cotransporter 2 inhibitors (SGLT2i)." (PMID 38610646, 2024). "The induction of fibrosis by the renin–angiotensin system is evident in multiple organ systems, including the eye, and the release of profibrotic cytokines and growth factors is common in the pathogenesis of both PVR and renal fibrosis." (PMID 37191619, 2023). "To further investigate whether the RAS system played important roles in the course of renal function improving and renal fibrosis inhibition via QDD, we examined the protein expression of AT1 and renin, respectively." (PMID 29849726, 2018). "We hypothesized that dCSF-CNs might affect the renin-angiotensin system (RAS) in kidney injury progression, with dCSF-CNs ablation potentially alleviating local RAS and renal fibrosis in rats after five-sixths nephrectomy (5/6Nx)." (PMID 30524304, 2018). "Thus, pro(renin) and PRR are involved in the development of renal fibrosis through multiple RAS-independent signaling pathways." (PMID 28753620, 2017). "A ramipril therapy that mainly targets the renin‒angiotensin‒aldosterone system (RAAS) to ameliorate AS-related kidney arterial hypertension effectively reduces TGFβ levels and thereby inhibits renal fibrosis, suggesting an important role of TGFβ in renal fibrosis." (PMID 40075271, 2025). "However, the pathogenesis of renal fibrosis has not been fully elucidated, and the existing intervention methods using renin-angiotensin system inhibitors are not effective in preventing or treating renal fibrosis, resulting in high mortality in patients with advanced CKD." (PMID 38680884, 2024).
preeclampsia (71 papers, 2009 to 2025). Preeclampsia is a hypertensive disorder of pregnancy that is characterized by new-onset hypertension with proteinuria presenting after 20 weeks of gestation, and depending on mild or severe forms may initially present with severe headache, visual disturbances, and hyperreflexia. "The renin rs5707 AC genotype in combination with a pre-pregnancy BMI ≥ 24 kg/m2 was significantly associated with an increased risk of preeclampsia and eclampsia." (PMID 39408215, 2024). "Women with SCD have also been reported to have a blunted renin-angiotensin-aldosterone system, causing significantly lower plasma expansion compared to normal pregnancies, and this mechanism has been linked to preeclampsia, IUGR, and low birth weight." (PMID 39322530, 2024). "For instance, recommending weight loss before conception to an obese woman because she carries a renin mutation that significantly increases the risk of preeclampsia with a high BMI." (PMID 39408215, 2024). "Studies suggest that the coronavirus binds to ACE-2 to enter the human cell, causing deregulation of the renin-angiotensin-aldosterone system and in the ratio between angiotensin-II and angiotensin-1-7, inducing manifestations suggestive of preeclampsia." (PMID 37494578, 2023). "Renin-angiotensin-aldosterone system (RAAS) directly or indirectly causes preeclampsia and thrombophilia through the fibrinolytic pathway that ultimately leads to RPL or infertility." (PMID 36532100, 2022). "One possible cause of preeclampsia has been attributed to alterations in the renin-angiotensin system, which has also been linked to cognitive decline." (PMID 33584345, 2021). "Of interest, the renin-angiotensin system (RAS) has been implicated in the development of preeclampsia and alterations in the RAS have been linked to cognitive decline and dementia." (PMID 33584345, 2021). "Changes in renin-angiotensin-aldosterone system are involved in pathogenesis of pregnancy complications such as preeclampsia and fetal loss." (PMID 27326417, 2016). "Although REN is an attractive candidate gene for preeclampsia, only a few studies have investigated associations of REN with preeclampsia." (PMID 20537141, 2010). "Preeclampsia pathogenesis has been associated with dysfunction of the renin-angiotensin-aldosterone (R-A-A) axis, resulting in decreased renin levels, increased angiotensin-converting enzyme (ACE) activity, decreased angiotensin II levels, and increased response to this enzyme." (PMID 35198246, 2022). "The renin-angiotensin system has also been implicated in the pathogenesis of preeclampsia." (PMID 35309508, 2022). "The important role RAS plays in pregnancy is further underlined by the fact that a preeclampsia-like model has been generated in female mice transfected with the human angiotensinogen gene and mated with males transfected with the human renin gene underlines this role." (PMID 19646248, 2009). "In preeclampsia, hypertension arises alongside increased systemic vascular resistance and afterload, involving the participation of the renin–angiotensin system (RAS) and immune mechanisms." (PMID 40703703, 2025). "AT1 autoantibodies also suppress circulating renin and aldosterone and their administration to mice can produce features of preeclampsia." (PMID 40497429, 2025). "While the RAS is typically upregulated in normal pregnancy, preeclampsia displays lower levels of renin, angiotensin II, and aldosterone." (PMID 40703703, 2025). "Consistent with earlier findings, maternal plasma renin and tetrahydroaldosterone concentrations are decreased in women with preeclampsia." (PMID 38966986, 2024). "Both models show that the excess secretion of renin and other renin-angiotensin-aldosterone system proteins or angiotensin-like peptides by the placenta can lead to the development of preeclampsia-like symptoms during mouse pregnancy." (PMID 37089425, 2023).
preeclampsia (continued). "In contrast, numerous studies have demonstrated that pregnancies with pre-eclampsia or gestational hypertension have lower plasma renin activity and lower aldosterone concentrations compared with normotensive pregnancies." (PMID 37628909, 2023). "Second, there is a typical deviation of the renin-angiotensin-aldosterone system with reduced plasma renin activity and the development of circulatory volume in preeclampsia." (PMID 36405831, 2022). "Mechanistically, we found that gestational hypertension in Stox1-KO mice resulted from activation of the uteroplacental renin-angiotensin system." (PMID 33301424, 2021). "In this pilot study, we use a transgenic mouse model that chronically overexpresses human angiotensinogen and renin (R+A+ mice) that displayed characteristics of preeclampsia such as proteinuria during gestation." (PMID 33584345, 2021). "In placentae from women with early-onset preeclampsia, miR-663 expression was increased; this miRNA also suppresses renal REN mRNA translation." (PMID 31551925, 2019). "It is well-established that circulating levels of active renin, Ang II and aldosterone are suppressed in women with preeclampsia compared with levels measured in normotensive pregnant women." (PMID 31551925, 2019). "In late-onset preeclampsia, the placental expression of miR-378, which is predicted to target REN and ACE mRNAs, miR-514b-3p, predicted to target AGT and AGTR1 mRNAs and miR-892c-3p, which targets AGT mRNA, were increased." (PMID 31551925, 2019). "Regulative function of renin-angiotensin system in blood vessel diameter probably plays an essential role in blood pressure regulation and so in preeclampsia." (PMID 30009143, 2018). "First trimester maternal blood proteomics uncovered the altered abundance of proteins of the renin–angiotensin and immune systems as well as complement and coagulation cascades in patients who subsequently developed both preterm and term preeclampsia." (PMID 30135684, 2018). "It is thought that administration of magnesium in the treatment of preeclampsia possibly reduces the activity of plasma renin and angiotensin converting enzymes resulting in low levels of renin, angiotensinogen, angiotensin II, and aldosterone." (PMID 30155474, 2018). "First trimester maternal blood proteomics uncovered an altered abundance of proteins of the renin-angiotensin and immune systems, complement, and coagulation cascades in patients with term or preterm preeclampsia." (PMID 30135684, 2018). "We tested the effects of relaxin in a transgenic rat model of preeclampsia, which is generated by mating female rats transgenic for human angiotensinogen with rats transgenic for human renin." (PMID 26963382, 2016). "Our rodent model of preeclampsia is based on the secretion of active renin from the placenta or the fetus, which interacts with circulating maternal hAGT leading to increased circulating and local angiotensin II." (PMID 26963382, 2016). "In an uncomplicated pregnancy, there is an increase in almost all the components of maternal RAS, including renin, angiotensin, and aldosterone, but these hormones are suppressed in preeclampsia." (PMID 23762576, 2013). "In normal pregnancy, components of renin-angiotensin-aldosterone system, including renin, angiotensin, and aldosterone, are increased, while these hormones are suppressed in preeclampsia." (PMID 23762576, 2013). "There is an increase in almost all the components of renin-angiotensin system during an uncomplicated pregnancy, but renin activity, angiotensin II, and aldosterone decrease in preeclampsia for reasons that are unclear." (PMID 22685661, 2012). "Specifically, preeclampsia-like symptoms were observed when females carrying human AGT were mated with males carrying human REN, whereas pregnant mice derived from other mating combinations did not manifest preeclamptic symptoms." (PMID 20537141, 2010).